FMR1-AS1 (FMR1 antisense RNA 1)
Synonyms: ASFMR1; FMR4; FMR5; FMR1-AS; FMR1AS
Gene: Long non-coding RNA gene on chromosome X (147,891,981 to 147,911,817, reverse strand). Ensembl gene ENSG00000268066.
Gene Ontology:
Biological process: negative regulation of apoptotic process
Diseases named in the same sentence as FMR1-AS1 in open-access papers:
FMR1-AS1 is named in the same sentence as 18 diseases in open-access papers, as found by Europe PMC text mining. Sharing a sentence is not in itself a finding about the gene and the disease. The quoted sentences say what the papers report.
esophageal squamous cell carcinoma (1 paper, 2023). Esophageal squamous cell carcinoma (ESCC) is a type of esophageal carcinoma (EC) that can affect any part of the esophagus, but is usually located in the upper or middle third. "The authors demonstrated that the X-linked lncRNA FMR1-AS1 (FMR1 Antisense RNA 1) was significantly overexpressed in CSCs within female ESCC (Esophageal squamous cell carcinoma) patients, and its overexpression can correlate with a poor clinical outcome." (PMID 36768150, 2023).
cancer (1 paper, 2022). A tumor composed of atypical neoplastic, often pleomorphic cells that invade other tissues. "LncRNAs, such as HOTAIR, H19, LncTCF7, LUCAT1, MALAT1, LINC00511, and FMR1-AS1, have been described as key regulators of stemness in cancer, allowing cancer cells to acquire this phenotype." (PMID 35954194, 2022).
FMR1-AS1 also shares sentences with these, for which no sentence is quoted: fragile X syndrome (6 papers); neuroblastoma (2); Parkinsonism (2); ataxia syndrome (1); attention deficit-hyperactivity disorder (1); autism (1); Ehlers-Danlos syndrome (1); fragile X tremor ataxia syndrome (1); Fragile X-Associated Primary Ovarian Insufficiency (1); Intellectual disability (1); Macroorchidism (1); Marfan syndrome (1); mitral valve prolapse (1); neurological disorders (1); premature ovarian failure (1); Tremor (1).